CXCL13 (C-X-C motif chemokine ligand 13)
Diseases named in the same sentence as CXCL13 in open-access papers (continued):
Sharing a sentence is not in itself a finding about the gene and the disease.
tumor (continued). "Finally, baseline levels of CXCL13 were unaltered between patients with different tumor localizations, TNM stages, tumor grading, resection status or sex but were significantly higher in patients with an impaired ECOG performance status." (PMID 36077611, 2022). "In addition, GPR56-positive cells expressed higher mRNA levels of CXCL13 and TGF-β1, two coordinating players in the anti-tumor immune response." (PMID 35804934, 2022). "We also investigated the specific association between FAM46C expression and chemokines and their receptors in pan-cancer and found that FAM46C expression was positively correlated with immune chemokines (CXCL9 and CXCL13) and immune chemokine receptors (CCR2 and CCR4) in most tumours (all p < 0.01)." (PMID 35222533, 2022). "In this study, we provide evidence that circulating levels of CXCL1, CXCL10 and CXCL13 are distinctly altered in patients with BTC and that serum CXCL13 levels, in particular, represent a promising candidate to predict outcomes following tumor resection." (PMID 36077611, 2022). "Not surprisingly, CD38 and CXCL13 were both highly correlated with T cells and other effector cells with tumor-killing abilities, which was consistent with their better prognosis." (PMID 35711935, 2022). "In addition to HEVs, chemokines secreted by tumor cells and other immune components, such as CXCL2, CXCL20, and CXCL13, promote the influx of B cells into the tumor." (PMID 35967441, 2022). "Additionally, by evaluating gene signatures in terminally exhausted CD8-positive TILs from various cancer types, an effector/exhaustive/tumor-reactive profile with a co-expression pattern of CD103, TIM-3 and CXCL13 was found." (PMID 36341460, 2022). "Accordingly, CXCL13 produced by CXCR5+/CD8+ TILs (through autocrine, paracrine or endocrine) might directly bind and induce cytotoxicity to lyse CXCR5+ tumor cells." (PMID 35392977, 2022). "In addition, exhausted CD4+ T cells, characterized by high expression of CXCL13 and BTLA, which are T follicular helper markers, were mainly collected from the tumour tissue." (PMID 35184398, 2022). "Because the injection of CXCL13 and CCL21 indicated a potential antitumor immune activity in orthotopic tumors, we explored whether coadministration of chemotherapy to induce tumor cell death, and perhaps release of tumor antigens, could impact tumor dynamics." (PMID 34252585, 2021). "At present, the roles of CXCL13, IDO1 and SPP1 in immune process of tumor have been studied." (PMID 34736480, 2021). "Moreover, in the NOD/SCID mice bearing A549-Luc-CXCL13 cells, CXCL13 recruits CXCR5+ CD68+ macrophages to the TME, where macrophages produce secreted phosphoprotein 1 (SPP1) to promote cell migration and tumor progression." (PMID 34947813, 2021). "Infiltrated CD4+ Tfh cells express CXCL13, which has been speculated to initiate GC formation and enhance TLS development by homing immune cells to peritumoral or tumor sites." (PMID 34947813, 2021). "In this study, the co-expression of CXCR5 in CAR-T was designed to not only increase the infiltration of CAR-T cells but also to mitigate potential off-tumor toxicity, due to our results that CAR-T only infiltrates into EGFR and CXCL13 double-positive tumor sites and produces a killing effect." (PMID 34553036, 2021). "For example, LFA-1+CXCR4+CXCR5+ tumor cells may interact with ICAM-1+, CXCL12+/CXCL13+ endothelial cells, and ICAM-1+CXCL13+ microglia." (PMID 34944954, 2021). "The CXCL13/CXCR5 axis not only modulates molecular events inside malignant cells to promote tumor initiation and progression, but also recruits multiple populations of lymphocytes to exert pro-tumor or anti-tumor immunity reactions in the TME." (PMID 34947813, 2021). "The increased expression of the exhaustion markers PD-1, Eomes, and TOX on tumor-infiltrating CD8+ T cells in mice lacking intratumoral IL-33 production by skin-derived Cxcl13-Cre+ FSCs is consistent with the phenotype of terminally exhausted T cells." (PMID 34354077, 2021).
tumor (continued). "The CXCL13/CXCR5 axis is involved in the regulation of cancer cell survival, apoptosis, proliferation, differentiation, migration, invasion, and adaptive immunity, and shows dichotomic anti- and pro-tumor functions in the TME." (PMID 34947813, 2021). "Anti-PD-1 therapy failed in a CXCL13-null mouse model of BLCA, whereas the wild-type model showed a good response, and the treatment with a combination of CXCL13 and anti-PD-1 successfully retarded tumor growth in another mouse model of OV." (PMID 34604032, 2021). "Our results indicated that the intratumoral CXCL13 expression could induce enhanced infiltration of CD4+, CD8+ T lymphocytes, and CD11b+CD11c+ DC in the 4T1 tumor microenvironment." (PMID 35693216, 2021). "Finally, single-cell RNA sequencing (RNA-seq) of clonal neoantigen-reactive CD8 tumor-infiltrating lymphocytes (TILs), combined with bulk RNA-seq analysis of CPI-responding tumors, identified CCR5 and CXCL13 as T-cell-intrinsic markers of CPI sensitivity." (PMID 33508232, 2021). "In this study, prompted by the observation of the CXCL13 overexpression on certain NSCLC patients, we implemented the strategy to co-express CXCR5 with the anti-EGFR-CAR-T to facilitate T cell migration to the tumor site." (PMID 34553036, 2021). "BTK inhibitors, such as Ibrutinib and other CXCL13 and CD20 antibodies could reduce tumor progression in B-cell leukemias." (PMID 33324975, 2021). "Therefore, we engineered an epidermal growth factor receptor (EGFR) CAR-T cell to express a second receptor CXCR5, to facilitate migration of CAR-T cells to the CXCL13-expressing NSCLC tumors, and to minimize EGFR-CAR-T possible off-tumor, on-target toxicity." (PMID 34553036, 2021). "CXCL13, in turn, potentiates the interaction between ILC3 and stromal cells, resulting in the increased production of RANKL on stromal cells, which promotes tumor cell migration and lymph node metastasis by the RANK-RANKL pathway." (PMID 34947813, 2021). "In particular, SLAMF6 and SLAMF1 expression in TAMs was increased by LFC = 2.1 and 3.5, both p.adj < 0.0001, and CXCL13 (LFC: 6.4, p.adj < 0.0001) and CXCR5 (LFC: 1.8, p.adj = 0.001) were highly upregulated in macrophages from the tumor compared to those from a normal lung." (PMID 33918618, 2021). "Of note, tumor‐infiltrating CXCL13‐positive ICs were positively correlated with CD20‐positive ICs and IGKC‐positive ICs, suggesting that the tumor infiltration of B cells and plasma cells was due to CXCL13 production by TILs." (PMID 33506656, 2021). "Predictors of poor outcomes included having tumours (P = 0.0193) and having a chronic onset (P = 0.0306), and predictors of relapses included having lower levels of CSF BAFF (P = 0.0491) and having a larger ratio of serum TGFβ1/serum CXCL13 (P = 0.0182)." (PMID 34872566, 2021). "As in the case of CXCL9, IRF5 (interferon regulatory factor 5) can bind to the promoter of CXCL13 and directly regulate its expression in mammary epithelial tumor cells leading to the infiltration of CD19+CXCR5+ B-cell and CD4+CXCR5+ T-cell to the tumor." (PMID 33304345, 2020). "Analyzing the amount of intratumoral CXCL13 after tumors have been excised does not clearly decipher if CXCL13 is a driver or responder to tumor progression." (PMID 33193299, 2020). "For example, elevated concentrations of proteins (e.g. PAI-1, CXCL13 and CXCL16) in the blood could indicate YAP activation in HCC tumor cells, which is detectable in about 30% of all HCC cases." (PMID 33097058, 2020). "Notably, some genes related to exhaustion were also overexpressed in tumor‐infiltrating Tregs including TYMS, KIAA0101, CXCL13, CD27, HLA‐DQB1, HLA‐DMA, ENTPD1, CD200, DUSP4, and ZBED2." (PMID 32659053, 2020). "CEA-TCB-treated tumors displayed a clear upregulation of several pro-inflammatory cytokines and chemokines [MIPα (CCL3), CXCL10, CXCL13, CXCL9, IL-16, and I-TAC (CXCL11)], an increase in intra-tumor CD3+, CD4+, CD8+ T-cells that express high levels of 4-1BB, PD-1, and upregulation of GZMB." (PMID 33330050, 2020).
tumor (continued). "BM466146 could promote the expression of CXCL-13 gene and increase the number of CD8+ T cells in tumor microenvironment, and activate their recognition and killing effect on tumor cells." (PMID 33585256, 2020). "BM466146 could regulate CXCL-13 by adsorbing hsa-miR-224-3p and inducing CD8+ T cells to accumulate in the tumor area which regulate immune response." (PMID 33585256, 2020). "Furthermore, it has been found that, in the presence of transforming growth factor-β (TGF-β), CD8+ T cells in peripheral blood can promote the recruitment of B cells to tumor tissues by upregulating the expression of CD103 and secreting CXCL13." (PMID 31662750, 2019). "Our data suggests that CXCL13+ TILs are functionally adapted to the tumor environment rather than being exhausted." (PMID 30505306, 2018). "IL-17A could stimulate ESCC tumor cells to produce much more chemokines, such as CCL2, CCL20 and CXCL13." (PMID 26942702, 2016). "Additionally, to estimate immune cell prevalence we used the average expression of the lymphocyte-specific genes GZMB, PRF1, CXCL13, IRF1, IKZF1, and HLA-E in each tumor sample." (PMID 27959926, 2016). "We found that in several works of this database, CXCL13 in tumor samples was elevated compared with their paired normal lung tissues or other normal controls." (PMID 26565418, 2015). "Using Western blot assays, we found that CXCL13 was much higher in the tumor samples than their adjacent normal lung tissues." (PMID 26565418, 2015). "The results demonstrated there existed a positive relationship between CXCL13 and Wnt/β-catenin signaling in HCC, and this mutual interaction might promote the level of each other and led to the tumor microenvironment formation." (PMID 26161394, 2015). "Immunohistochemical staining for CXCL13 from 30 patients revealed that all of the tumor cells were negative for CXCL13." (PMID 25966773, 2015). "We showed that DEX inhibited CXCL13 production by epithelial cells and SPP1 production by TAMs, inhibited the EMT, reduced the tumor burden and prolonged the life span of the mice, revealing a new mechanism for this existing drug." (PMID 26565418, 2015). "Similarly, CXCL5, CXCL13, CCL1, CCL7 and CCL26 in WF collected from patients with T1–2 tumor tend to be higher than those with Tis, and the profiles of CXCL13, CCL27, MMP-1 and MMP-7 in WF from N1–3 patients tend to be higher than those with N0." (PMID 26313265, 2015). "In the present study, CXCL13 and CXCR5 were up-regulated in tumor tissues, especially in poorly differentiated tumors, suggesting that both CXCL13 and CXCR5 are correlated with HCC and their up- regulation were probably the results of integrated factors in worse tumor environment." (PMID 26517519, 2015). "In paired comparisons of tumour vs normal mucosa IR gene expression (n = 144), there was a trend for higher expression of CXCL9 (Wilcoxon test, p = 0.05) and lower expression of CD3Z, CXCL13 and IGHM in the malignant tissue." (PMID 25970543, 2015). "In this model, greatly elevated levels of CXCR5 are seen on the surface of tumor cells, and greatly elevated levels of murine, but not human, CXCL13 are seen in the serum and ascites of animals with tumors." (PMID 23936541, 2013). "High levels of murine, but not human, CXCL13, also were seen in these animals, and tumors contained tumor-infiltrating cells that stained positively for murine CXCL13 by immunohistochemistry." (PMID 23936541, 2013). "The expression of D2-40 was observed in partial or focal tumor cells in all cases while CXCL-13 was absent." (PMID 23761812, 2013). "Expression of CXCL13 was only rarely observed in tumor cells of THRLBCL-like NLPHL as well as THRLBCL, but never in typical NLPHL (pattern A)." (PMID 24244368, 2013). "CXCL13, expressed in follicular T helper cell derived lymphomas, was 1.7- and 1.9-fold upregulated in LP cells of typical NLPHL and THRLBCL-like NLPHL, respectively, as well as 1.5-fold in tumor cells of THRLBCL." (PMID 24244368, 2013).
tumor (continued). "The high levels of CXCR5 and murine CXCL13 that are seen in the 2F7 model thus raises the possibility, although does not prove, that murine CXCL13 (possibly produced by tumor-infiltrating cells) acts to promote tumor growth." (PMID 23936541, 2013). "In 60-100% of the cases, the tumour cells express CD10, CXCL13 and PD-1." (PMID 22568881, 2012). "It was observed that CXCL13 (3,17x) and PEG10 (9,38x and 4,38x, p = 0,05) were both up-regulated in progressive disease and possibly this up-regulation can contribute to impairment of the T-lymphocyte mediated anti-tumor response in progressive disease." (PMID 22295114, 2012). "In accordance with RNA expression levels, CXCL13 protein was commonly found in tumour samples, whereas it was absent from all healthy breast tissues analysed." (PMID 18781150, 2008). "We also did not observe any significant correlations between tumour RNA expression of CXCL13 or CXCR5 and clinical characteristics of individual patients (data not shown)." (PMID 18781150, 2008). "Notably, compared with the PD‐L1− tumor group, the upregulated differentially expressed genes (DEGs) in the CD8‐C2‐Texterm subset from PD‐L1+ tumor group included exhaustion‐related genes such as HAVCR2, CXCL13, PDCD1, TIGIT, LAG3, BATF, GNLY, and CTLA4." (PMID 41194450, 2026). "Responders (CR/PR) exhibited robust cytotoxic T-cell activation characterized by up-regulation of GNLY, GZMB, and CXCL13, whereas non-responders (SD) uniquely showed persistent overexpression of HSPA1B, a stress-response gene associated with tumor progression and immune suppression." (PMID 42158872, 2026). "Furthermore, evidence suggests that CXCL13, together with CXCR5, may play a crucial role in regulating tumor occurrence and metastasis via the PI3K/AKT pathway, as demonstrated in studies on CRCs." (PMID 40943634, 2025). "This superior anti-metastatic activity is likely attributable to the combinatorial expression of CD40L, CD93, and CXCL13 and the promoter optimization of the LVV, which may enhance antigen presentation, T cell recruitment, and improved immune modulation in the tumor microenvironment." (PMID 41295503, 2025). "In addition, tumor regression (and proportion of CXCL13+ Tex) was not correlated with the interval between ICI administration and surgery." (PMID 41045934, 2025). "However, adding PD‐1 blocking antibody did not enhance tumor‐killing efficacy for either control CAR T cells or CXCL13 CAR T, most likely due to the limited induction of exhaustion during short‐term in vitro co‐culture." (PMID 40492496, 2025). "Additionally, the proportion of Treg cells and CXCL13+ T cells was elevated in the IDC stage, and tumor cells frequently interacted with T cells through co-inhibitory axes like NECTIN2/TIGIT, resulting in T cell exhaustion and the establishment of an immunosuppressive TME." (PMID 40867511, 2025). "The fact that CXCL13 was not significantly increased in the aggregates may be because there are also T cells in the diffuse portion of the tumour." (PMID 39462771, 2025). "While anti-tumor T cell subsets, such as T_C1_Cytotoxic cells, were enriched in the low-PCD group, the high-PCD group exhibited a significant accumulation of exhausted T cells, characterized by the expression of exhaustion markers such as LAG3, HAVCR2, CTLA4, TIGIT, and CXCL13." (PMID 40740783, 2025). "Functionally, CXCL13 CAR T cells demonstrated reduced expression of exhaustion markers, including PD‐1 and TIM3, enhanced mitochondrial health, and elevated ATP production, which collectively contributed to their enhanced cytotoxic activity against tumor cells in vitro." (PMID 40492496, 2025). "Additionally, we found increased expression of the CXCL13 program in CD4+ resident memory and CD8+ exhausted subsets, which may be consistent with the expansion of tumor-reactive CD8+ T cells." (PMID 39417106, 2024). "However, tumor-reactive T cells in AML did not exhibit significant expression of CXCL13 or classical exhaustion molecules." (PMID 39243082, 2024).
tumor (continued). "Furthermore, our study identifies TLS-associated cell types (B lineage cells, CD4_C8_CXCR5 and CD8_C8_CXCL13 T cells, and CXCL13+ CAFs) and TCA signatures (EBVhigh-TCA-wP) as biomarkers for the prognosis and immunotherapy response of NPC, corroborating TLS’s contribution to tumour development." (PMID 39231979, 2024). "Remarkably, these two chemokines were also highlighted by a recent meta-analysis that evaluated existing biomarkers of ICB response, suggesting that CXCL9 and CXCL13 are indeed the strongest individual transcriptomic predictors of ICB response independent of tumor type." (PMID 38722600, 2024). "Their result proves that human and mouse lung adenocarcinomas pull out the production of tumor-binding antibodies and, moreover, identified endogenous retrovirus (ERV) envelope glycoproteins as a strong anti-tumor antibody target, which probably requires CXCL13-dependent TLS formation." (PMID 39769125, 2024). "Furthermore, HPV+ tumor cells could directly induce CXCL13 expression in CD4+T cells, differentiating CXCL13+CD4+T cells, as evident in our co-culture assays." (PMID 39105803, 2024). "Our study utilized SiT, scRNA‐seq, and T‐cell receptor (TCR) analyses of tumor and LN tissues to demonstrate that the temporal heterogeneity of the spatial CD74 isoform correlates with the expanded enrichment of C1QC+ TAMs and CD8+CXCL13+ Tex cells in LN metastasis of ESCC." (PMID 39312471, 2024). "We propose a model where an effective response to ICI is marked with CXCL13+ CD8 T cell-driven recruitment of highly diversified, CXCR5+ B cell clones whose subsequent (tumor) antigen presentation activities induce and sustain the activation of tumor-reactive CD4 Tfh and CD8 T cells." (PMID 37435085, 2023). "Moreover, chemokine (CXC motif) ligand 13 (CXCL13) in tumors and plasma is correlated with the level of ICAM‐1 and ICI efficacy, suggesting that CXCL13 might be involved in the ICAM‐1‐mediated anti‐tumor pathway." (PMID 37097643, 2023). "Elevated CXCL13 expression in IE1 was confirmed in IMC on both transcript and protein levels and the proportions of CXCL13+ T cells measured by scRNA-seq and IMC on two separate pieces of the same tumor were highly correlated, indicating that CXCL13+ T cell frequency was a tumor-wide characteristic." (PMID 36609566, 2023). "Notably, after in-vitro expansion in the presence of exogenous TGFβ (6 days), a considerable CXCL13 production was found only in cells from the tumor, mainly characterized by a PD1+CD28− TRM phenotype, and not in NT tissue." (PMID 37898752, 2023). "Importantly, CXCL13 increase does not per se indicate TLS formation, as tumor-reactive T cells identified through CXCL13 expression can also be a source that expands upon treatment in ICI-responders." (PMID 37794264, 2023). "The CXCR2-ADRA1A function module generated from our data included several immune-related genes, such as CXCL5, CXCL13, RGS12, and CXCR1, indicating that the DNA methylation function module might involve in the immune response regulation in the tumor microenvironment of sMPLC." (PMID 36611170, 2023). "Since another team has demonstrated that this tumor-specific CD39+ CD4+ TILs population expresses CXCL13, PD-1 and TOX exhaustion makers and this population could contribute to tumor-specific CD8+ T cell proliferation and DC maturation through in situ reactivation with PD-1 blockade." (PMID 35008422, 2022). "Multivariate Cox regression analysis including age, tumor size, gender, and recurrence indicated that high level of CXCL13 may not be a significant predictor of OS (HR = 1.569; 95% CI, 0.974–2.527; p = 0.0642)." (PMID 35570844, 2022). "Results suggest that AKAP12, APOL3, CXCL13, CXCL9, GBP4, and LRIG1 may act as tumor suppressors." (PMID 35677536, 2022).